CRP (C-reactive protein)
Diseases named in the same sentence as CRP in open-access papers (continued):
Sharing a sentence is not in itself a finding about the gene and the disease.
colorectal cancer (continued). "The aim of the present study was therefore to examine the relationship between tumour T-lymphocyte subset infiltration, circulating concentrations of C-reactive protein and cancer-specific survival in patients who had undergone potentially curative resection for colorectal cancer." (PMID 15700032, 2005). "There have been no previous reports of the relationship between high serum CRP levels and the risk for colorectal cancer in a population-based cohort study of Japanese." (PMID 16127232, 2005). "Colorectal cancer patients may have elevated C-reactive protein (CRP) levels indicating a systemic inflammatory response." (PMID 15569387, 2004). "Serum CRP levels correlate with survival in colorectal cancer patients." (PMID 15569387, 2004). "We studied longitudinally inflammatory reactions and serum C-reactive protein (S-CRP) levels in 52 colorectal cancer patients treated with a median of six 3-weekly cycles of raltitrexed 1.5–3.0 mg m−2 combined with oral carmofur (1-hexylcarbomoyl-5-fluorouracil) 300–400 mg m−2 on cycle days 2–14." (PMID 12237767, 2002). "Postoperative day 3 CRP was significantly lower after robotic surgery compared with laparoscopy [MD - 13.18 mg/l (95% CI - 22.29, - 4.08), p = 0.005), this was further demonstrated in colorectal cancer surgery subgroup analysis [MD -17.22 (95%CI -26.28, -8.17), p = 0.0002 I2= 0%]." (PMID 42223505, 2026). "Additionally, supplementation reduced (P < 0.05) CRP concentrations in lung and colorectal cancers." (PMID 40523478, 2025). "Also, for the specific group of patients with colorectal cancer, a preoperative plasma level of CRP ≥ 10 mg/L was a prognostic factor for inferior survival three years after surgery (multivariate hazard ratio 2.40, 95% confidence interval 1.20–4.81, p = 0.014)." (PMID 33920422, 2021). "In addition, the prognostic nutritional index (PNI, based on serum albumin and lymphocyte counts) and the serum C-reactive protein (CRP)/serum albumin ratio (CAR) were shown to be effective predictors of postoperative complications after colorectal cancer surgery." (PMID 33879101, 2021). "High leukocyte numbers, neutrophil-to-lymphocyte ratios (NLRs) and C-reactive protein (CRP) levels have been associated with poorer outcomes in many cancers, such as testicular germ cell tumors, squamous cell carcinoma, soft tissue sarcoma, and colorectal cancer." (PMID 30867256, 2019). "CRP and IL-6 also correlated to cytokine intensity in gastric cancer and certain clinical characteristics such as more advanced tumor stage in gastric and colorectal cancer, shorter survival in colorectal, PC and lung cancer, and cachexia in patients with colorectal, pancreatic and lung cancer." (PMID 30038723, 2018). "JNK pathway-associated phosphatase expression has been reported to be associated with disease activity and outcome in SLE and colorectal cancer, and it is commonly accepted that CDAI, Mayo index for UC, CRP, and ESR are important indicators for clinical disease activity in IBD patients." (PMID 28725226, 2017). "Given that high-sensitivity CRP is a circulating marker for inflammation, the lack of a consistent association with colorectal neoplasia raises questions on its use as a marker of the inflammatory process associated with colorectal cancer." (PMID 26321888, 2015). "Although concentrations of inflammatory biomarkers, especially CRP, have been associated with colorectal cancer risk in some studies, this association does not seem to have a robust support without hints of bias (e.g., selective reporting, reverse causation, residual confounding)." (PMID 26321888, 2015). "With the combination of CRP status and total harvested number of lymph nodes in stages II or III colorectal cancer, better stratification may aid in identifying high-risk patients in order that adjuvant therapy be tailored to increase the number of positive patient outcomes." (PMID 23833661, 2013).
colorectal cancer (continued). "Therefore, in this study, we examined whether elevated CRP levels could be used to identify a subset of patients with very poor prognosis in stage II or III colorectal cancer." (PMID 23833661, 2013). "Thus, serum MMP-9 could be another valid marker of colorectal cancer progression, especially if combined with IL-8, (and CRP)." (PMID 22848630, 2012). "Moreover, compared with patients undergoing potentially curative resection for colorectal cancer in the same institution, the proportion of patients who had an elevated circulating concentration of C-reactive protein (>10 mg l−1) preoperatively was lower in the present study (13 vs 28%)." (PMID 16685271, 2006). "RESULTS: Serum CRP levels were not clearly associated with the risk of colorectal cancer." (PMID 16127232, 2005). "Higher serum CRP levels were not apparently associated with higher risk for colorectal cancer." (PMID 16127232, 2005). "There was no clear association between serum CRP levels and the risk of colorectal cancer." (PMID 16127232, 2005). "Besides melanoma, high CRP serum levels are known to indicate shorter median survival in patients suffering from other tumours such as renal cell carcinoma or colorectal carcinoma." (PMID 15280926, 2004). "Indeed, there is evidence that the systemic inflammatory response (as evidenced by C-reactive protein) predicts recurrence, overall and cancer-specific survival, independent of stage, in patients who have undergone curative resection for colorectal cancer." (PMID 12915865, 2003). "Blood protein biomarkers, such as carcinoembryonic antigen (CEA) and C-reactive protein (CRP), have been widely employed in colorectal cancer (CRC) research." (PMID 41395603, 2025). "We evaluated the joint relationship of post-operative C-reactive protein (poCRP) and a tumor immune-cell-score (IS) with overall survival (OS) and CRC-specific survival (CSS) in 680 colorectal cancer (CRC) patients recruited in Germany." (PMID 41291131, 2025). "Neutrophil–lymphocyte ratio, C-reactive protein, and Glasgow Prognostic Score on POD3 can predict postoperative complications in patients who undergo minimally invasive surgery for colorectal cancer." (PMID 40192855, 2025). "CRP-to-albumin ratio (CAR), a biomarker related to inflammation and nutrition, has been demonstrated as a prognostic factor in various cancers including colorectal cancer, gastric cancer, pancreatic cancer, esophageal cancer, and ovarian cancer." (PMID 40416620, 2025). "Inflammation-related plasma proteins such as C-reactive protein (CRP), IL-6 (interleukin-6), TNF-alpha (tumor necrosis factor) and its receptors, adiponectin play complex roles in colorectal cancer development." (PMID 41464635, 2025). "Inflammatory biomarkers, including CRP, IL-6, TNF - α and its receptors, adiponectin and leptin, play complex roles in colorectal cancer development." (PMID 39980561, 2025). "Neutrophil–lymphocyte ratio, C-reactive protein, and Glasgow Prognostic Score on POD3 can predict postoperative complications in patients who undergoing minimally invasive surgery for colorectal cancer." (PMID 40192855, 2025). "In a study of 103 colonoscopy-diagnosed colorectal cancer patients, ColonSecure testing demonstrated superior detection efficiency of methylation levels compared to CEA, CRP, and CA19-9 in 89 patients." (PMID 39155349, 2024). "The systemic inflammatory response (SIR), defined as elevated levels of circulating C-reactive protein (CRP), is an important predictor of impaired survival in colorectal cancer." (PMID 39613865, 2024). "A raised level of C-reactive protein (CRP) has been found to be an indicator of poor prognosis in several cancers, including esophageal carcinoma, carcinoma of the stomach, colorectal cancer, hepatocellular carcinoma, renal cancer, and pancreatic tumor." (PMID 36900365, 2023).
colorectal cancer (continued). "Xu Jiayi, Wang Jinkai and Zhou Lu discussed the value of serum C-reactive protein (CRP), sugar chain antigen 19-9 (CA19-9) and carcinoembryonic antigen (CEA) in the preoperative diagnosis of colorectal cancer." (PMID 36873937, 2023). "The OPS, a new prognostic score incorporating C-reactive protein (CRP), serum albumin and total lymphocyte counts (TLC), was first used to predict outcome for colorectal cancer following resection." (PMID 37464311, 2023). "As far as we know, this is the first study in which serum levels of pro-inflammatory cytokines (IL-1β, IL-6, TNF-α), inflammatory markers (ESR CRP and fibrinogen), and tumor markers (CEA and CA 19.9) have been compared in colorectal cancer." (PMID 38137862, 2023). "It has been reported that Osaka prognostic score (OPS), based on C-reactive protein (CRP), total lymphocyte counts (TLC) and albumin (ALB), was relevant to prognosis in colorectal cancer." (PMID 35300627, 2022). "Surprisingly, CRP, CysC, TC and CA125 were found to be dramatically higher in the cognitive impaired group compared with those in the cognitive normal group in colorectal cancer patients." (PMID 35448193, 2022). "Recently, another measurement method of the systemic inflammatory response, the lymphocyte to C-reactive protein (CRP) ratio (LCR) has been proposed for patients with rectal cancer, colorectal cancer, and gastric cancer." (PMID 36266627, 2022). "We noticed that the CCL2 and CCL4 areas under the ROC curve (0.634; 0.630, respectively) in the entire group of colorectal cancer were highest from all newly tested parameters, but lower than AUC for CEA and CRP." (PMID 35407400, 2022). "Lymphocyte-C-reactive Protein Ratio (LCR) has been demonstrated as a promising new marker for predicting surgical and oncological outcomes in colorectal carcinoma (CRC)." (PMID 35870933, 2022). "And CRP/ALB ratio has been used as a prognostic factor in variety of solid cancers including esophageal cancer, lung cancer, gastric cancer, colorectal cancer and so on." (PMID 34001160, 2021). "We noticed that the CCR3 area under the ROC curve (0.683) in the total group of colorectal cancer was the highest from all the tested parameters but lower than the AUC for CEA and CRP." (PMID 34204490, 2021). "Knowing that interleukin-6 (IL-6) and C-reactive protein (CRP) factor into the development of colorectal cancer (CRC), we aimed to assess IL-6 and CRP's relationship with the stage and differentiation of CRC." (PMID 33552492, 2021). "The NLR and C-reactive protein (CRP) level have been proven to be prognostic factors for NSCLC and other tumors, including hepatocellular carcinoma, colorectal cancer, and esophageal cancer." (PMID 35096967, 2021). "The ratio of C-reactive protein (CRP) to albumin (CAR) has a significant correlation with postoperative complications and acts as a predictor in patients with pancreatic cancer and colorectal cancer." (PMID 33727917, 2021). "We assessed the effect of surgical resection of colorectal cancer (CRC) on perioperative plasma vitamin D (25OHD) and C-reactive protein (CRP) level." (PMID 31023832, 2020). "Recently, the combination of C-reactive protein and albumin, known as the Glasgow Prognostic Score (GPS) has been evaluated pre-operatively in patients undergoing potentially curative surgery for colorectal cancer." (PMID 17923866, 2007). "Thus, high serum CRP levels did not appear to increase the risk of colorectal cancer." (PMID 16127232, 2005). "Furthermore, given that C-reactive protein concentrations are primarily determined by interleukin-6 concentrations, it is of interest that recent studies have shown that increased circulating concentrations of interleukin-6 in colorectal cancer are related to its production by the tumour." (PMID 12915865, 2003). "CRP is not the only biomarker that has proven useful in the postoperative monitoring of colorectal cancer." (PMID 40392334, 2025).
colorectal cancer (continued). "However, a strength of this study is that it is a consecutive series of colorectal cancer patients and is one of the first studies to use the CCI scale for analyzing postoperative complications in relation to CRP-4POD." (PMID 40392334, 2025). "However, more recently published studies found a correlation between a high postoperative inflammatory response (CRP and interleukin-6) and worsened long-term survival in patients undergoing LAS and open surgery for UICC stage I–III colorectal cancer." (PMID 40383853, 2025). "CRP, procalcitonin, TNF‐α, IL‐6, IL‐10, and WBC have been used as the most common markers of inflammatory stress, and Chen used these indices to compare the efficacy of laparoscopic surgery and conventional surgery in the treatment of colorectal cancer." (PMID 38351544, 2024). "CRP could potentially promote CEA, MMP1 and MMP2 by stimulating LOX-1 receptors in colorectal cancer." (PMID 38071306, 2023). "CRP levels were more significant in the diabetic group than in the non-diabetic group with colorectal cancer (49.9 mg/L vs. 39.1 mg/dL), supporting this fact." (PMID 37627906, 2023). "Furthermore, in this study, the same bacteria that correlated with IL-6, CRP, and TNF-α levels in the GI microbiota dysbiosis mice have been detected in fecal and tumor samples of patients with breast, cervical, and colorectal cancer." (PMID 35740687, 2022). "In colorectal cancer (CRC), a link between serum MMP-8 and CRP levels has been reported." (PMID 35328734, 2022). "The predictive values of the C-reactive protein (CRP) and procalcitonin (PCT) levels for postoperative infectious complications were investigated in patients who underwent elective laparoscopic resection of colorectal cancer." (PMID 32785845, 2021). "Systemic inflammatory factors, such as lymphocytes, monocytes and neutrophils, and blood biochemical indicators related to nutritional status, such as C-reactive protein levels (CRP) and albumin levels (ALB), are valuable prognostic indicators for cancers including colorectal cancer." (PMID 34150609, 2021). "In this retrospective observational study, there was a significant association between type of anaesthesia, and the magnitude of the postoperative day 2 CRP in patients who underwent open but not laparoscopic surgical resection for colorectal cancer." (PMID 32348308, 2020). "CRP levels on POD3 were elevated to the same level in both LG and OG groups with and without complications after colorectal cancer surgery, and CRP levels on POD3 were not final predictors of complications." (PMID 31429742, 2019). "The present pilot study reports a possible association between preoperative CPET-derived measures of exercise tolerance, and the preoperative systemic inflammatory response, but not postoperative CRP in patients undergoing surgery for colorectal cancer." (PMID 29983927, 2018). "Furthermore, the modified Glasgow Prognostic Score (mGPS), which comprises the serum C-reactive protein (CRP) and serum albumin levels, has been demonstrated as a favourable prognostic index for colorectal cancer (CRC) patients." (PMID 30419863, 2018). "As for the blood test results, the blood levels of total cholesterol, triglycerides, glucose, total bilirubin, aspartate transaminase (AST), C-reactive protein (CRP), CEA, and CA19-9 differed significantly between the colorectal cancer patients and healthy volunteers." (PMID 28179577, 2017). "A similar behavior in a different contest has been reported in patients undergoing colorectal cancer surgery who display an early reduction of ficolin-1, followed by a rebound at longer time points (up to 2 weeks) with no relation to CRP changes." (PMID 26792363, 2016). "CRP is an independent prognostic marker in patients with stage I–III, II or III colorectal cancer." (PMID 23833661, 2013). "CRP was previously shown to predict the incidence of cancer of any type, lung and colorectal cancer, but not breast or prostate cancer." (PMID 23937962, 2013).
colorectal cancer (continued). "CRP is related to systemic inflammation, but its effect on colorectal cancer is not clear." (PMID 36299603, 2022). "They identified five key factors (neutrophils, lymphocytes, platelets, albumin, and CRP) reflecting systemic inflammation derived from NLR, PLR and CAR, and examined the best combination with highest accuracy to predict oncological outcomes in colorectal cancer patients." (PMID 33507925, 2021). "Reduced ApoA1 and raised CRP have also been described in a number of systemic conditions including colorectal carcinoma, in which serum ApoA1 level showed a strong negative correlation with systemic markers of inflammation including serum CRP and serum interleukin‐8 levels." (PMID 31693246, 2020). "However, previous research performed in non-orthopedic patients (i.e., cardiovascular and colorectal cancer) demonstrates that the NLR associates with other common indices of systemic inflammation, such as C-reactive protein and interleukin-6." (PMID 27848053, 2017). "A recent trial described modelling in patients with colorectal cancer and liver metastases where combining circulating nucleosomes levels (24 h post radiation treatment) with pre-therapeutic levels of CRP and AST improved the prognostic model (compared to CRP and AST alone)." (PMID 28075351, 2017). "In this study, we aimed to determine whether CRP provides more accurate prognostic information than that offered by the existing staging systems or tumor markers in stages I–III, or in subgroups of stages II or III colorectal cancer patients." (PMID 23833661, 2013). "Previously, we also reported that CRP levels reflect IL-6 production in colorectal cancer tissues and predict poor prognosis in colorectal cancer patients, particularly in stage I or II patients who are not usually candidates for postoperative adjuvant chemotherapy." (PMID 23833661, 2013). "Furthermore, combining the LNR or harvested lymph node number and the preoperative CRP status may provide more accurate data for predicting poor prognosis and identify patients requiring further, intense chemotherapy in stage III colorectal cancer." (PMID 23833661, 2013). "In particular, an elevated C-reactive protein, measured either prior to or following curative surgery, has been shown to predict recurrence and overall survival, independent of stage, in patients with colorectal cancer." (PMID 15597096, 2005). "For example, higher concentrations of circulating C-reactive protein (CRP), a highly sensitive but non-specific marker of elevated inflammatory response, were associated with a higher risk of several cancers, including breast, lung, prostate, ovarian and colorectal cancer." (PMID 35012533, 2022). "Interestingly, we found that the 1009 predicted protein targets of SNT included CRP but not COL12A1 in BATMAN; COL12A1 may not have been studied very much, as only a few studies have shown its association with Colorectal Cancer and colon cancer." (PMID 32982747, 2020). "In addition, the CRP-positive group had significantly poorer cancer-specific survival compared with the CRP-negative group in stage III colorectal cancer patients with an inadequate number of examined lymph nodes (<12) or LNR <0.15 (log-rank test; lymph node number examined, p<0.05; LNR, p<0.01)." (PMID 23833661, 2013). "The aim of the present study was to assess whether or not an elevated circulating C-reactive protein concentration has prognostic value independent of conventional clinicopathological criteria in patients undergoing potentially curative resection for colorectal cancer." (PMID 15150596, 2004). "Notably, there is also a report which shows no significant prognostic value when considering serum CRP level for predicting cancer recurrence rate in stage II and III colorectal cancer." (PMID 27733196, 2016).